IL27 (interleukin 27)
Diseases named in the same sentence as IL27 in open-access papers (continued):
Sharing a sentence is not in itself a finding about the gene and the disease.
Miscarriage (3 papers, 2023 to 2025). A pregnancy that ends at a stage in which the fetus is incapable of surviving on its own, defined as the spontaneous loss of a fetus before the 22th week of pregnancy. "Our findings suggest that elevated IL-27 levels may be a risk factor for recurrent spontaneous abortion (RSA)." (PMID 40141672, 2025). "Elevated IL-17 and IL-27 levels were observed in healthy pregnancies, whereas lower levels were seen shortly after a miscarriage." (PMID 40141672, 2025). "Increased levels support the idea that IL-27 is related to the immunological processes in miscarriages." (PMID 40141672, 2025). "This study addresses an important gap by examining the differences in IL-2, IL-27, and IL-17 levels between recurrent miscarriage and healthy pregnancy in detail." (PMID 40141672, 2025). "In contrast, IL-17 levels were significantly reduced in spontaneous abortion patients compared to healthy pregnant women, whereas IL-27 levels were significantly increased." (PMID 40141672, 2025). "Additionally, the changes in IL-2, IL-17, and IL-27 in recurrent miscarriages can contribute to our understanding of the roles of these cytokines in immune responses and inflammation processes." (PMID 40141672, 2025).
myasthenia gravis (3 papers, 2018 to 2024). Myasthenia gravis (MG) is a rare, clinically heterogeneous, autoimmune disorder of the neuromuscular junction characterized by fatigable weakness of voluntary muscles. "In this study, we detected the IL-27 serum levels in 59 myasthenia gravis (MG) patients and 35 healthy controls (HCs)." (PMID 33312724, 2020). "Jeong and his colleagues demonstrated that higher IL-27 levels were observed in early-onset myasthenia gravis (EOMG) and the TAMG subpopulation contains lower IL-27 levels." (PMID 33312724, 2020).
osteomyelitis (3 papers, 2022 to 2023). An acute or chronic inflammation of the bone and its structures due to infection with pyogenic bacteria. "Given the association between IL-27 expression and S. aureus osteomyelitis in patients, we next measured IL-27 in mice with S. aureus osteomyelitis induced using a well-established transtibial model." (PMID 36028492, 2022). "Remarkably, exogenous IL-27 treatment decreased the severity of S. aureus osteomyelitis, including reductions in abscess formation and bone loss." (PMID 36028492, 2022). "Indeed, in this small patient cohort, formal analyses of IL-27 as a diagnostic biomarker using receiver operator characteristic (ROC) curve analysis revealed good prediction accuracy for identifying S. aureus osteomyelitis, as indicated by the area under the curve (AUC) of 0.922 (P < 0.000 1)." (PMID 36028492, 2022). "However, our study indicates that IL-27 could be an diagnostic marker associated with S. aureus osteomyelitis and could help to predict septic complications." (PMID 36028492, 2022). "At the onset of S. aureus osteomyelitis, osteoblasts and macrophages induce IL-27 secretion via TLR activation, and this process is dependent on the autoregulatory IL-27/IL-27Rα signaling pathway." (PMID 36028492, 2022). "Collectively, these results identify a novel phenomenon of IL-27 expression by osteoblasts immediately following S. aureus infection of bone and suggest a protective role of systemic IL-27 in osteomyelitis." (PMID 36028492, 2022). "In this study, we measured systemic levels of IL-27 in serum from patients with S. aureus osteomyelitis." (PMID 36028492, 2022). "We report that IL-27 expression was induced in patients with S. aureus osteomyelitis and that elevated serum IL-27 correlated with septic death in these patients." (PMID 36028492, 2022). "From these observations, it is conceivable that IL-27 exhibits time-dependent functions in host immunity, ranging from protective immunity in acute S. aureus osteomyelitis to suppressive immunity during chronic infection." (PMID 36028492, 2022). "Second, we need to examine the complex temporal changes in the infiltrating immune cells in the bone marrow niche, which contribute to IL-27/IL-27R crosstalk during S. aureus osteomyelitis." (PMID 36028492, 2022). "Here, we examined whether IL-27 is an essential cytokine involved in the pathogenesis of S. aureus osteomyelitis." (PMID 36028492, 2022). "We next examined whether systemic IL-27 mediates bacterial clearance during S. aureus osteomyelitis in our murine model." (PMID 36028492, 2022). "Interleukin-27 is a pleiotropic cytokine whose functions during bacterial infections remain controversial, and its role in patients with S. aureus osteomyelitis is unknown." (PMID 36028492, 2022). "Remarkably, IL-27 levels immediately following septic death were 60-fold higher than those in healthy individuals (P < 0.05), suggesting that IL-27 could be useful in predicting S. aureus osteomyelitis-induced septic death." (PMID 36028492, 2022). "Currently, the contribution of IL-27 to host immunity during S. aureus osteomyelitis is unknown." (PMID 36028492, 2022). "Cytokines and chemokines play a notable role in the pathogenesis of both diseases, such as neutrophils, IL8, IL-27, IL23, MMPs, and serum TNF, which play a key role in the pathogenesis of osteomyelitis and DFU." (PMID 37904457, 2023). "However, endogenous IL-27 is not sufficient to influence host susceptibility to osteomyelitis." (PMID 36028492, 2022). "Furthermore, the abundance of IL-27 suppresses RANK expression and inhibits osteoclast differentiation, leading to decreased bone osteolysis during chronic osteomyelitis." (PMID 36028492, 2022).
osteomyelitis (continued). "Exogenous IL-27 administration for Staphylococcus aureus-infected osteomyelitis not only induces accumulation of pro-inflammatory IL-17-producing RORγt+ neutrophils, leading to reduced abscess formation, but also inhibits RANKL-induced osteoclast activation to relieve osteomyelitis osteolysis." (PMID 37860014, 2023). "To test this hypothesis, we evaluated S. aureus osteomyelitis in WT and IL-27Rα−/− mice with and without exogenous IL-27 induction by intramuscular injection of rAAV-IL-27p28 or rAAV-GFP, respectively." (PMID 36028492, 2022).
osteoporosis (3 papers, 2023 to 2025). A condition of reduced bone mass, with decreased cortical thickness and a decrease in the number and size of the trabeculae of cancellous bone (but normal chemical composition), resulting in increased fracture incidence. "In addition, elevated levels of IL-27 have been recognized as a risk factor particularly for osteoporosis, with evidence suggesting a causal link of IL-27 with the disease." (PMID 41329541, 2025). "It upregulates the expression of the RNAKL repressor Id2, which was also demonstrated in female patients with osteoporosis whose serum IL-27 levels were reduced along with decreased Egr2 expression, suggesting a potential new anti-osteoporosis treatment strategy." (PMID 37475866, 2023).
papilloma (3 papers, 2016 to 2021). A benign epithelial neoplasm that projects above the surrounding epithelial surface and consists of villous or arborescent outgrowths of fibrovascular stroma. "Indeed, in transgenic mice harboring the mutated KRAS in the K15+ follicular stem cells, IL27 promoted faster visible papilloma incidence and induced higher ETAR expression in the CD11b-positve cells in the pre-malignant skin." (PMID 27738312, 2016). "TGFβ signaling, a marker of cells going through tissue regeneration, was increased in papillomas derived from IL27-treated mice, as determined by the phosphorylation of the effector protein pSMAD2." (PMID 27738312, 2016). "More importantly, the number of proliferating K15-positive stem cells was increased in papillomas derived from IL27-treated mice when compared to control-treated mice." (PMID 27738312, 2016). "In summary, IL27 can promote pre-malignant skin markers and papilloma formation via upregulation of ETAR-positive CD11b-cells in the skin." (PMID 27738312, 2016). "IL27-induced papilloma initiation was compromised in IL27RA−/− mice, suggesting that IL27 signaling through its receptor, IL27RA, is needed to promote papilloma initiation." (PMID 27738312, 2016). "As expected, wildtype mice treated with IL27 via gene therapy had a higher incidence and developed more papillomas when compared to control counterparts." (PMID 27738312, 2016). "Interestingly, the lack IL27 signaling (IL27RA−/−) during the initiation of carcinogenesis reduced the incidence of papilloma formation over time when compared to wildtype mice." (PMID 27738312, 2016). "In the K15-KRASG12D model, zibotentan can reverse IL27-driven changes in the pre-malignant niche and initiation of papillomas, suggesting that the contribution of ETAR signaling in epithelial cells is unlikely to explain the ETAR-dependent pro-tumor effects of IL27." (PMID 27738312, 2016). "Interestingly, using in vivo studies, IL27 promoted papilloma incidence primarily through IL27 signaling in bone-marrow derived cells." (PMID 27738312, 2016).
schistosomiasis (3 papers, 2013 to 2023). An infectious disease caused by parasitic trematodes of the genus Schistosoma that colonize human blood vessels and release eggs that can cause granulomatous reactions leading to acute (swimmer's itch or acute schistosomiasis syndrome) or chronic disease. "The Th1/Th2 cytokines in chronic patients were not significantly different from those in healthy people, while patients with advanced schistosomiasis had higher levels of IL-2, IL-23 and IL-27 and lower levels of IL-18 and IFN-γ." (PMID 37887717, 2023). "IL-27 showed an increasing trend, with a significant difference between the patients with advanced schistosomiasis and the healthy controls, but no statistical difference was found compared with the chronic patients." (PMID 37887717, 2023). "Still, these regulatory properties of IL-27 cannot be adopted universally, as disruption of the IL-27 signaling pathway did not alter egg-induced immunopathology in an experimental schistosomiasis model." (PMID 23855879, 2013). "Immunological approaches using WSX-/- mice (receptor chain of IL27) point to a reduction in IFN-γ levels compared with wild-type mice during acute and chronic stages of mansonic schistosomiasis but with no impact on liver damage." (PMID 32078636, 2020).
spondyloarthritis (3 papers, 2018 to 2025). "Consistent with our imputed findings, IL-27 treatment prior to disease onset in the HLA-B27-transgenic rat spondyloarthritis model inhibited spondyloarthritis development through suppression of IL-17/TNF production by CD4 + T-cells." (PMID 40709250, 2025).
tuberculous pleurisy (3 papers, 2021 to 2025). "Combined detection with other cytokines enhances diagnostic accuracy, while IL-27 and other IL-12 family members exhibit notable advantages in diagnosing specific TB presentations such as tuberculous pleurisy." (PMID 40243848, 2025). "The concentration of IL-27 in PEs was found to be increased in tuberculous pleurisy and several adult studies have investigated the diagnostic value of IL-27 for TPEs, but the reported results remain controversial." (PMID 35967581, 2022). "For the first time, our study has shown the diagnostic role of IL-27 in pediatric tuberculous pleurisy." (PMID 35967581, 2022). "In this study, we aimed to evaluate the potential value of IL-27 in pediatric tuberculous pleurisy by detecting its levels in pleural fluid and serum." (PMID 35967581, 2022). "In this study, we showed for the first time the value of IL-27 in discriminating pediatric tuberculous pleurisy from SMPPE." (PMID 35967581, 2022). "However, the specificity of IL-27 was relatively lower and it is necessary to find a more specific marker in tuberculous pleurisy of children." (PMID 35967581, 2022). "This indicates that compared to patients without TPE, patients with tuberculous pleurisy have a 58-fold higher chance of being ADA.IL-27 assay positive." (PMID 33436672, 2021). "However, no related studies have demonstrated the role of IL-27 in pediatric tuberculous pleurisy." (PMID 35967581, 2022).
viral encephalitis (3 papers, 2019 to 2025). Encephalitis resulting from viral infection. "IL-12p70 (p = 0.0320) was also elevated in the encephalitis group and IL-27 (p = 0.0221) in the meningitis group compared to the control group." (PMID 40517242, 2025).
viral myocarditis (3 papers, 2016 to 2020). Myocarditis that is caused by an infection with a viral agent. "Similarly, IL-27 inhibited the differentiation of Th17 cells, ameliorated the symptoms and improved of the survival rate of viral myocarditis in mice." (PMID 30176160, 2018). "In addition, there were reports showed that IL-27 negatively regulated the development of Th17 during chronic inflammation of the central nervous system in mice that chronically infected with T. gondii, or in mice that coxsackievirus-B3-induced viral myocarditis." (PMID 27994590, 2016).
airway hyperresponsiveness (2 papers, 2021 to 2024). "IL-27 is involved in steroid-resistant airway hyperresponsiveness." (PMID 34234781, 2021). "Therefore, we hypothesized that IL-27 affects airway inflammation and airway hyperresponsiveness in asthmatic mice by affecting the dendritic CD39 /ATP axis." (PMID 38117410, 2024).
alveolitis (2 papers, 2015 to 2024). "The addition of anti-IL-27 antibody exacerbated the disease severity, downregulated survival, and upregulated mortality rate and expression of hydroxyproline and type I and III collagen, whereas injection of IL-27 relieved disease activity and degree of alveolitis." (PMID 38566992, 2024).
ankylosing spondylitis (2 papers, 2020 to 2024). An autoimmune chronic inflammatory disorder characterized by inflammation in the vertebral joints of the spine and sacroiliac joints. "Serum levels of IL-27 were much higher in patients with AS as compared to that in healthy controls, and were related to serum levels of VEGF and Bath Ankylosing Spondylitis Disease Activity Index (BASDAI)." (PMID 38566992, 2024).
autoimmune encephalitis (2 papers, 2011 to 2024). Inflammation of the brain secondary to an immune response triggered by the body itself. "Several subsequent studies reported the effect of IL-27 as a potent inhibitor of Th17 differentiation in autoimmune encephalitis and cerebral toxoplasmosis." (PMID 38314317, 2024). "In mice with Opn-deficient DCs, substantially elevated levels of IL-27 are produced and Opn−/− mice develop delayed experimental autoimmune encephalitis with a Th1 rather than Th17-dominated response." (PMID 22242114, 2011).
autoimmune thyroid disease (2 papers, 2021). Inflammatory disease of the thyroid gland due to autoimmune responses leading to lymphocytic infiltration of the gland. "Our data suggest a possible detrimental effect of IL-27, which is likely to contribute to the development of autoimmune thyroid disease in individuals with T1DM." (PMID 34439776, 2021). "In line with this assumption, studies of single nucleotide polymorphisms have confirmed an association between IL-27 and the SIRT1 gene with autoimmune thyroid diseases." (PMID 34439776, 2021). "Moreover, the sirtuin 1 was positively correlated with IL-27 levels in women with T1DM and HD, which suggests an association with thyroid autoimmunity." (PMID 34439776, 2021).
bacterial sepsis (2 papers, 2015 to 2025). "The understanding of cells specifically responsible for IL-27 during neonatal bacterial sepsis is incomplete." (PMID 40682363, 2025). "In this body of work, we directly address the knowledge gap by specifically characterizing the cells that produce IL-27 in tissues with high levels of E. coli harvested from neonatal mice experiencing bacterial sepsis." (PMID 40682363, 2025). "In the studies presented here, we followed our standard infection strategy to investigate IL-27 producers during neonatal bacterial sepsis by IVIS-CT, flow cytometry, and single-cell sequencing." (PMID 40682363, 2025). "This further provides essential information needed to support IL-27 as a therapeutic target for neonatal bacterial sepsis." (PMID 40682363, 2025). "We observed important differences in quantity and between the cells comprising the IL-27 profile across tissues during neonatal bacterial sepsis." (PMID 40682363, 2025). "Given this, the dearth of other pediatric studies investigating the value of IL-27, for this purpose, and the need for more effective biomarkers in bacterial sepsis, we hypothesized that IL-27 can effectively serve as a diagnostic biomarker among the critically ill pediatric population." (PMID 26514771, 2015).
cerebrovascular disease (2 papers, 2024 to 2025). "In cardiovascular and cerebrovascular diseases, IL-27 acts as a double-edged sword, activating STAT3 pathways to reduce inflammation while also being implicated in pathological vascular remodeling." (PMID 39906735, 2024). "In this context, the role of IL-27 in cerebrovascular diseases has gained increasing attention." (PMID 39906735, 2024).
Chagas disease (2 papers, 2017 to 2024). A parasitic infection caused by Trypanosoma cruzi. "In this regard, Natale (2021) suggests that this is due to the dysregulation between IL-7 and IL-27, and their receptors, which promotes the state of exhaustion of the T-cell response in the late phases of Chagas disease." (PMID 39452741, 2024). "Here, we showed that IL-27 seems to have a protective role in Chagas disease." (PMID 29033934, 2017). "Indeed, polymorphic sites at Ebi3 gene in Chagas disease patients were associated with more severe forms of CCC, suggesting that IL-27 may have a protective effect on the pathogenesis of the human disease." (PMID 29033934, 2017). "To confirm the importance of IL-27 in Chagas disease and understand whether polymorphic sites at Ebi3 gene might contribute to the severity of the disease, we assessed whether the two most prevalent polymorphic regions at the Ebi3 gene were related to the clinical manifestations of Chagas disease." (PMID 29033934, 2017). "Its production has also been reported in other studies in patients with Chagas disease who do not have severe heart disease, suggesting that IL-27 production has a tolerogenic effect in these cases." (PMID 39452741, 2024).
chronic hepatitis C (2 papers, 2014 to 2025). "CD4P/I(hi) T cells also expressed several genes not typical of the Tfh subset, including EBI3, a subunit of the IL-27, IL-35, and IL-39 cytokines, and the inflammatory cytokine IL32 associated with liver injury in chronic hepatitis C." (PMID 40956619, 2025).
depression (2 papers, 2023 to 2025). "Our findings revealed significantly elevated circulating levels of IL-6, IFN-γ, IL-17, TNF-α, IL-10, and IL-27 in individuals with depression compared to healthy controls." (PMID 41561993, 2025). "Surprisingly, IL-27 has not been extensively investigated in depression and does therefore not surface in large metanalyses on cytokine alterations in depression." (PMID 37101546, 2023).
E. coli infection (2 papers, 2024 to 2025). "Neonatal models show that IL-27 deficiency improves bacterial clearance, reduces inflammation, and enhances survival during E. coli infection." (PMID 40861493, 2025).
endometrial cancer (2 papers, 2019 to 2021). Primary or metastatic malignant neoplasm involving the endometrium (mucous membrane that lines the endometrial cavity). "Importantly, this cytotoxicity was favored by the stimulation of rapamycin-mediated autophagy, a signal that was amplified by IL-27, further promoting a suppression of endometrial cancer progression." (PMID 31850214, 2019). "However, IL-27 could not directly impair cell death and the growth of endometrial cancer cells, but in combination with rapamycin and cisplatin amplifies these effects." (PMID 31850214, 2019).